CLDN5 (claudin 5)
Description:
Plays a major role in tight junction-specific obliteration of the intercellular space.
Synonyms: TMDVCF; AWAL; TMVCF; CPETRL1; BEC1
Tractability: Antibody: its Gene Ontology location is reachable by antibodies, with high confidence; UniProt places it where antibodies can reach, with medium confidence; UniProt predicts a signal peptide or a membrane-spanning region.
Gene: Protein-coding gene on chromosome 22 (19,523,024 to 19,527,545, reverse strand). Ensembl gene ENSG00000184113.
Subcellular location: Cell junction, tight junction; Cell membrane
Pathways (Reactome):
Cell-Cell communication: Tight junction interactions
Gene expression (Transcription): RUNX1 regulates expression of components of tight junctions
Gene Ontology:
Molecular function: protein binding; identical protein binding; structural molecule activity
Biological process: cell-cell junction assembly; establishment of blood-retinal barrier; maintenance of blood-brain barrier; negative regulation of angiogenesis; negative regulation of cell migration; negative regulation of gene expression; negative regulation of vascular permeability; positive regulation of bicellular tight junction assembly; positive regulation of cell population proliferation; positive regulation of establishment of endothelial barrier; positive regulation of gene expression; transforming growth factor beta receptor signaling pathway; calcium-independent cell-cell adhesion; face morphogenesis; learning; outflow tract morphogenesis; roof of mouth development; tight junction assembly; myelination; response to ethanol
Cellular component: apicolateral plasma membrane; bicellular tight junction; cell-cell junction; cortical actin cytoskeleton; plasma membrane; tight junction; cell junction; membrane; lateral plasma membrane; paranode region of axon; Schmidt-Lanterman incisure
Genetic constraint (gnomAD): Loss-of-function variants: 6 observed, 2.04 expected, observed/expected ratio (o/e) 2.95. That is too few expected variants to judge how well the gene tolerates losing a copy. Missense variants: 225 observed, 284.03 expected, observed/expected ratio (o/e) 0.79, 90% interval 0.71 to 0.88. Synonymous variants: 156 observed, 138.36 expected, observed/expected ratio (o/e) 1.13, 90% interval 0.99 to 1.29.
Homologues: Orthologues: macaque CLDN5 (98% identical), dog CLDN5 (94% identical), pig CLDN5 (93% identical), mouse Cldn5 (92% identical), rat Cldn5 (91% identical), guinea pig CLDN5 (88% identical), tropical clawed frog cldn5 (60% identical), zebrafish cldn5a (58% identical), zebrafish cldn5b (55% identical). Paralogues in human: CLDN3 (55% identical), CLDN6 (53% identical), CLDN9 (53% identical), CLDN4 (47% identical), CLDN1 (43% identical), CLDN7 (42% identical), CLDN8 (42% identical), CLDN14 (39% identical), CLDN19 (39% identical), CLDN17 (39% identical), CLDN15 (33% identical), CLDN2 (33% identical), and 10 more.
Diseases named in the same sentence as CLDN5 in open-access papers:
CLDN5 is named in the same sentence as 253 diseases in open-access papers, as found by Europe PMC text mining. Sharing a sentence is not in itself a finding about the gene and the disease. The quoted sentences say what the papers report.
Stroke (68 papers, 2013 to 2025). Sudden impairment of blood flow to a part of the brain due to occlusion or rupture of an artery to the brain. "Claudin-5 dysfunction has also been implicated in many neurological disorders, including Alzheimer’s disease, multiple sclerosis, stroke, epilepsy, and schizophrenia." (PMID 37490345, 2023). "It is possible that the more severe BBB dysfunction in occludin-deficient mice after stroke is due to the lower expression levels of claudin-5 and ZO-1 in the brain endothelial cells." (PMID 36806348, 2023). "The overall increase in BBB permeability after a stroke is closely linked to the decreased expression of tight junction proteins, such as claudin-5, occludin and ZO-1, among others." (PMID 34857032, 2021). "The location of stroke in the anterior part of the brain blood supply is associated with high blood levels of occludin and claudin 5 in the acute phase of stroke." (PMID 33182224, 2020). "We show that RA associates to worse stroke-outcome via exacerbated BBB degradation by decrease of the TJPs claudin-5 and occludin." (PMID 30778120, 2019). "Furthermore, occludin-deficient mice showed decreased claudin-5 and neovascularization after stroke." (PMID 36806348, 2023). "Our findings are in line with the involvement of vitamin D on tight junction proteins in the blood-brain barrier, where vitamin D deficiency decreased the expression of occludin and claudin-5 and is suggested to complicate stroke severity and chronic consequences in rat." (PMID 31930458, 2020). "Among these, tight junction-associated proteins such as occludin, claudin-5 and ZO-1, which are essential for BBB integrity, have been explored as potential predictors of stroke severity and outcomes." (PMID 41408503, 2025). "Mounting evidence signifies that BBB disruption correlates with occludin and claudin-5 degradation in brain tissue, as well as the presence of occludin in the bloodstream following a stroke episode." (PMID 39119484, 2024). "Herein, we have demonstrated that a biomarker panel of TJ proteins (OCLN, Claudin-5, and ZO-1) combined with a stroke severity scale, NIHSS, can be a good prediction model to differentiate between IS patients and SMs." (PMID 39595521, 2024). "Previous research has shown that the BBB is disrupted during a stroke, resulting in alterations in the concentrations and distributions of Claudin-5, OCLN, ZO-1, and other BBB building blocks." (PMID 39595521, 2024). "This re-localization of Cldn5 also occurs in brain microvascular endothelial cells collected from current stroke patients and in zebrafish." (PMID 39330552, 2024). "Occludin and claudin-5 mRNA decreased rapidly 3 h after stroke onset, while ZO-1 mRNA decreased gradually." (PMID 36806348, 2023). "In rodent models of stroke and traumatic brain injury, claudin-5, occludin, and ZO-1 were down-regulated with the opening of the BBB leading to extravasation of serum proteins." (PMID 37185751, 2023). "On the contrary, aged VEGF-LOF led to a significantly decreased claudin-5 expression 72 h after stroke, thus disrupting the blood–brain barrier integrity." (PMID 35175562, 2022). "Numerous reports in a variety of models (e.g., SCI, stroke, MS) suggest that imatinib alters endothelial tight junction protein expression (e.g., claudin 5, occludin, e-cadherin, connexin 43, beta-catenin) and improves vascular integrity." (PMID 35528149, 2022). "Claudin-5 is a crucial BBB TJ protein responsible for increased paracellular permeability in experimental stroke settings if disrupted." (PMID 36085043, 2022). "Compared to Sham, stroke brains displayed pronounced reduction of Claudin-5 protein expression in the IL LVCP (p < 0.05)." (PMID 35413993, 2022). "Muscone and (+)-borneol reduced cerebral infarct volume and cerebrovascular leakage with claudin 5 protection in mice after stroke, largely due to inhibiting ROS accumulation and inflammatory infiltrate of microglia." (PMID 35892657, 2022).
Stroke (continued). "In the ischemic core levels of Claudin-5, VE-cadherin and β-catenin were maintained in LoF animals whereas Stroke-Ctrl mice had elevated levels of these proteins in correlation with the increased permeability observed." (PMID 34046769, 2021). "We have shown that cerebral ischemia can cause Cav-1-mediated redistribution and endocytosis of Claudin-5, which causes BBB disruption in the early stages of stroke." (PMID 34531766, 2021). "A recent study showed that claudin-1 replaced claudin-5 at the TJs of brain capillary endothelial cells during the regeneration phase after stroke." (PMID 34795584, 2021). "In the ischemic core, a significant induction of Claudin-5 expression was observed in Stroke-Ctrl mice versus Sham-Ctrl and Stroke-HIF-1 LoF mice." (PMID 34046769, 2021). "In this study, TJAP-1 and Claudin-1 exhibited a significant increase in CRTC1 KO mice compared with WT mice, leading to BBB damage by Claudin-5/Claudin-1 dysregulation in the CRTC1 KO brain after stroke." (PMID 34880207, 2021). "Levels of VE-cadherin, an adherens junction (AJ) component that regulates Claudin-5 expression via β-catenin signaling, were also induced in correlation with increased β-catenin expression in Stroke-Ctrl mice." (PMID 34046769, 2021). "The stroke mice (p = 0.003) and the BF+stroke mice (p = 0.04) expressed lower levels of claudin-5 on the ipsilateral sides than contralateral sides (stroke: 0.42 ± 0.02 and BF+stroke: 0.33 ± 0.02) of hippocampi." (PMID 33187248, 2020). "Dysregulation of claudin-5 and changes in the endothelial permeability were demonstrated in a number of pathological processes, including stroke, inflammation, and brain tumors." (PMID 32645833, 2020). "In our study, the concentrations of claudin 5 and occludin were higher in patients whose stroke was located in the area of carotid artery vascular supply, as compared with those whose stroke was located in the area supplying the basilar artery." (PMID 33182224, 2020). "Considering that we measured the parameters before the end of the first day of stroke, the occurrence of occludin and claudin-5 was most probably due to ischemic reperfusion injury." (PMID 33182224, 2020). "The BF+stroke group (0.33 ± 0.02) also expressed a lower level of claudin-5 on the contralateral side than sham group (0.45 ± 0.01, p < 0.001) and BF group ((0.43 ± 0.02, p = 0.004)." (PMID 33187248, 2020). "BF+stroke group had the highest number microglia/macrophages and the lowest level of claudin-5 among all groups and had fewer pericytes than BF group." (PMID 33187248, 2020). "In this regard, a recent study showed that claudin-1 replaces claudin-5 at the TJ of brain capillary endothelial cells during the regeneration phase after stroke." (PMID 32138745, 2020). "Compared to the BF mice (0.44 ± 0.02), the stroke (p = 0.008) and BF+stroke (p = 0.003) mice expressed lower levels of claudin-5 on the hippocampi ipsilateral side to stroke lesion." (PMID 33187248, 2020). "Mice subjected to BF and stroke also had lower levels of tight junction protein, claudin-5, and fewer vascular pericytes in the hippocampi than mice subject to single injury, suggesting that BF exacerbates BBB breakdown." (PMID 33187248, 2020). "In all patients, the plasma concentrations of claudin-5, occludin, and ZO-1 on the first day of stroke were examined and next, the mean concentrations were analyzed and compared between subgroups created on the basis of demographical and clinical features." (PMID 33182224, 2020). "The BF+stroke group also expressed a lower level of claudin-5 than the stroke mice on the ipsilateral side of stroke (p = 0.04)." (PMID 33187248, 2020). "During stroke, claudin-5 is removed from the endothelium in a caveolin-dependent process as well as in cultured endothelial cells treated with the cytokine CC-chemokine ligand 2 (CCL2) before further processing in early but not late endosomes." (PMID 30691500, 2019).
Stroke (continued). "Further, the present data indicated a time critical reaction of Cldn5 in the neocortex with a stable condition at 4 h and a significantly down-regulated mRNA level towards 24 h after stroke induction." (PMID 31089963, 2019). "The tPA-DHI combination significantly reduced degradation of claudin-5, occludin and ZO-1 at 24 h after stroke." (PMID 29681849, 2018). "The expression of the tight junction proteins claudin-5 and occludin were measured by Western blot in isolated microvessels from brains of control and obese ob/ob mice at 4 or 24 h post-stroke." (PMID 26823471, 2017). "MMP-2/9 has been shown to mediate BBB disruption by degrading TJ proteins such as occludin and claudin-5 in an animal stroke model and an in vitro ischemic model." (PMID 25815722, 2015). "qPCR of RiboTag-IP’dmRNA from isolated microvessels after stroke revealed enrichment of astrocyte markers Aqp4 and Gfap, as well as depletion of vascular markers including Pecam1, Cldn5 (endothelial cells), Pdgfrb (pericytes), and Acta2 (vascular smooth muscle cells)." (PMID 39796165, 2025). "In agreement with this, our results showed that the ZO‐1 and Claudin 5 were decreased both in vitro and in vivo stroke models, and that PBMT could reverse these changes." (PMID 38421088, 2024). "Indeed, we found that VDR ablation in microglia/macrophages markedly impaired BBB integrity after stroke, as evidenced by reduced expression of endothelial tight junction proteins, ZO-1 and Claudin-5, 3 days after MCAO." (PMID 36890539, 2023). "Thus, analysis of the spatiotemporal dynamics of occludin expression showed that it decreased, as did claudin-5 and ZO-1, in brain endothelial cells from ischemic lesions after stroke in wild-type mice." (PMID 36806348, 2023). "We then assessed whether stroke induces changes of the blood-CSF barrier TJ integrity by probing for ZO-1 and claudin 5 protein expression by immunostaining." (PMID 38107410, 2023). "Furthermore, expression of claudin-5 and ZO-1 also decreased in the peri-infarct area at 24 h after stroke." (PMID 36806348, 2023). "In our study, quantitative real-time PCR analyses revealed that, in wild-type mice, the mRNA level of occludin, as well as those of claudin-5 and ZO-1, decreased starting from the acute phase at 3 h after stroke, and the decline continued into the chronic phase 48 days after stroke." (PMID 36806348, 2023). "We considered two possibilities: one is that occludin deficiency directly decreases claudin-5 and ZO-1, and the other is that occludin deficiency exacerbates tissue damage, including BBB destruction, after stroke, which secondarily leads to more severely reduced claudin-5 and ZO-1." (PMID 36806348, 2023). "The reduced Claudin-5 protein expression was detected in the stroke Veh-control ChP (p < 0.01)." (PMID 35413993, 2022). "However, studies have reported that CLDN5 (claudin 5) is abnormally accumulated in the cytoplasm of BMECs in stroke patients, accompanied by autophagy activation." (PMID 35281512, 2022). "The analysis of post-stroke human and mouse blood microvessels indicated that Claudin-1 was highly expressed in leaky brain microvessels and there was a corresponding decrease in Claudin-5 expression." (PMID 35887162, 2022). "Consistently, in our study, we found that muscone and (+)-borneol reduced cerebral infarct volume and cerebrovascular leakage with claudin 5 protection in mice after stroke, largely due to inhibiting ROS accumulation and inflammatory microglia recruitment in the peripheral infarct area." (PMID 35892657, 2022). "Collectively, our results demonstrate that butorphanol tartrate displays beneficial capacities on Hcy-induced BBB disruption by upregulating the expressions of KLF5 and Claudin-5, suggesting a novel pharmacological function of butorphanol tartrate on brain cardiovascular diseases such as stroke." (PMID 35245993, 2022).
Stroke (continued). "Thus to understand why Stroke-HIF-1 LoF mice had better BBB functionality we performed immunohistochemistry to visualize Claudin-5 and ZO-1 organization at the vessel walls." (PMID 34046769, 2021). "Multiple compressions and Tukey’s post hoc analysis showed that compared to the sham group (0.45 ± 0.03), the stroke group (0.33 ± 0.03, p = 0.002) and BF+stroke group (0.25 ± 0.04, p < 0.001) had lower levels of claudin-5 in hippocampi ipsilateral to the stroke injury." (PMID 33187248, 2020). "In this study, we showed that the BF shortly before stroke significantly decreased the level of claudin-5 and the vascular pericyte-coverage in the hippocampi of the stroke mice, indicating that BF can exacerbate BBB breakdown in the hippocampi of stroke mice as well." (PMID 33187248, 2020). "Increased blood–brain barrier permeability is a common pathological symptom after ICH, which could explain the differential expression of CLDN5 in patients with stroke." (PMID 31392102, 2019). "Mimicking hypoxic conditions of stroke in vitro revealed downregulation of claudin-5 and altered localisation accompanied by decreased TEER; while hypoxic conditions in the retina downregulated claudin-5 and increased the extravasation of low molecular weight tracers." (PMID 30691500, 2019). "Valproic acid and sodium butyrate (class I, IIa and III inhibitor) repressed the nuclear translocation of NFκB subunit p65, mitigate MMP9 activity and restore the BBB integrity after stroke by regulating the expression of tight junction proteins, claudin-5, and ZO-1." (PMID 31543756, 2019). "For example, neurodegenerative diseases such as stroke and Alzheimer's disease are closely related to changes in TJ-related proteins, and experimental studies have shown that the expressions of ZO-1 and Claudin-5 exhibit long-term decreases during seizures." (PMID 30258402, 2018). "Claudin-5 expression on blood vessels has been reported to be discontinuous following stroke and has been shown to be located on a small percentage of infiltrating leukocytes in a model of multiple sclerosis, leading to the appearance of a punctate immunostaining pattern." (PMID 29649307, 2018). "Myeloperoxidase (MPO) staining identified hypochlorous acid-producing neutrophils in the brain, found both within claudin 5-stained vasculature and in the parenchyma, were significantly increased after stroke in old subjects (> 71 years old) compared to young (≤ 71 years old) stroke subjects." (PMID 29752550, 2018). "After stroke, deletion of astrocytic CCL2 rescued several phenotypes by Slc4a4 loss, including infarct size, BBB leakage, increased CD31 intensity, impaired tight-junctional marker expression (Claudin-5), and enhanced transcellular transport (pCav-1, Cav-1) surrounding the peri-lesion region." (PMID 38709635, 2024). "Although above results suggested Cav-1 plays an important role in ZO-1 and Claudin-5 redistribution and degradation post-stroke, whether Cav-1 directly or indirectly affects ZO-1 and Claudin-5 is still ambiguous, especially in permanent stroke model." (PMID 36855156, 2023). "Therefore, BF enhanced the reduction of claudin-5 expression in the hippocampi of stroke mice." (PMID 33187248, 2020). "In several models of neurological diseases, especially stroke or cerebral ischemia-reperfusion injury and Alzheimer's disease a link was established between decreased expression, disrupted organization or redistribution of claudin-5 and occludin and increased BBB permeability." (PMID 26834555, 2015). "When comparing the relationship between the IS group and SM group and the severity of a stroke, we found that IS patients had significantly higher serum GFAP, NFL, OCLN, Claudin-5, and ZO-1 levels in both groups as compared to SMs." (PMID 39595521, 2024). "After 24 h pMCAo, the fluorescence intensity of Claudin-5 and ZO-1 presented weak and unclear in BMV from ischemic cortex post-stroke, while partly salvaged by BMSC-EVs and BEC-EVs treatments." (PMID 36855156, 2023).